Y_RNA (Y RNA )
Gene: Miscellaneous RNA gene on chromosome 20 (49,920,597 to 49,920,694, reverse strand). Ensembl gene ENSG00000199490.
Homologues: Orthologues: chimpanzee Y_RNA (99% identical), macaque Y_RNA (93% identical). Paralogues in human: Y_RNA (89% identical), Y_RNA (88% identical), RNY3 (87% identical), Y_RNA (87% identical), RNY3P2 (86% identical), Y_RNA (86% identical), Y_RNA (85% identical), RNY3P1 (84% identical), RNY3P13 (84% identical), RNY3P14 (84% identical), RNY3P9 (84% identical), Y_RNA (84% identical), and 91 more.